MSTO1 (misato mitochondrial distribution and morphology regulator 1)
Description:
Involved in the regulation of mitochondrial distribution and morphology. Required for mitochondrial fusion and mitochondrial network formation.
Synonyms: LST005; FLJ10504; MST; misato; MMYAT
Tractability: PROTAC: ubiquitination databases record sites on it; its protein half-life has been measured.
Gene: Protein-coding gene on chromosome 1 (155,563,235 to 155,616,511, forward strand). Ensembl gene ENSG00000125459.
Subcellular location: Mitochondrion outer membrane; Cytoplasm
Subcellular location (Human Protein Atlas): Cytosol
Gene Ontology:
Molecular function: protein binding
Biological process: mitochondrion distribution; mitochondrion organization; positive regulation of mitochondrial fusion
Cellular component: cytoplasm; cytosol; mitochondrial outer membrane; mitochondrion
Genetic constraint (gnomAD): Loss-of-function variants: 20 observed, 34.97 expected, observed/expected ratio (o/e) 0.57, 90% interval 0.4 to 0.83. The synonymous counts are far from expectation, so gnomAD's model fits this gene poorly and the ratio says little. Missense variants: 273 observed, 387.21 expected, observed/expected ratio (o/e) 0.71, 90% interval 0.64 to 0.78. Synonymous variants: 117 observed, 152.33 expected, observed/expected ratio (o/e) 0.77, 90% interval 0.66 to 0.9.
Gene-disease validity (ClinGen):
ClinGen rates the evidence that MSTO1 causes each of these diseases.
mitochondrial disease (autosomal recessive): Definitive.
Homologues: Orthologues: chimpanzee MSTO1 (98% identical), pig MSTO1 (85% identical), rabbit MSTO1 (84% identical), dog MSTO1 (83% identical), guinea pig MSTO1 (81% identical), mouse Msto1 (78% identical), rat Msto1 (69% identical), zebrafish msto1 (46% identical), tropical clawed frog msto1 (43% identical), Drosophila melanogaster mst (30% identical).
Diseases named in the same sentence as MSTO1 in open-access papers:
MSTO1 is named in the same sentence as 25 diseases in open-access papers, as found by Europe PMC text mining. Sharing a sentence is not in itself a finding about the gene and the disease. The quoted sentences say what the papers report.
Ataxia (8 papers, 2017 to 2026). Ataxia refers to impaired coordination of voluntary muscle movement. "Variants in the MSTO1 gene cause a rare disease characterized by early-onset myopathy and cerebellar ataxia, with almost 30 cases reported worldwide." (PMID 36035138, 2022). "Mutations in the MSTO1 gene are associated with a rare disease condition characterized by early-onset myopathy and cerebellar ataxia." (PMID 36468072, 2022). "In this study, we presented two patients with novel MSTO1 compound heterozygous mutations in a Chinese family with cerebellar ataxia." (PMID 36468072, 2022). "Dominant MSTO1 variants have been found in patients with myopathy, ataxia, optic atrophy, and developmental delay, while recessive variants induce myopathy and cerebellar ataxia." (PMID 33426505, 2020). "Recently, MSTO1 was described as a cytosolic mitochondrial fusion protein, and pathogenic variants in MSTO1 have been reported to cause ataxia, muscle weakness, cerebellar atrophy and pigmentary retinopathy." (PMID 31463572, 2019). "The WES analysis in our families with myopathy and ataxia revealed that mutations of MSTO1 can be a new genetic cause for rare human disease, impairing the mitochondrial dynamic maintenance circuit." (PMID 28544275, 2017). "We identified a c.22G > A (p.Val8Met) mutation of MSTO1 in patients with minor physical abnormalities, myopathy, ataxia, and neurodevelopmental impairments." (PMID 28554942, 2017). "We report here the first families carrying recessive variants in the MSTO1 gene: compound heterozygous mutations were identified in two sisters and in an unrelated singleton case, who presented a multisystem complex phenotype mainly characterized by myopathy and cerebellar ataxia." (PMID 28544275, 2017). "Different compound heterozygous variants in MSTO1 were found by WES also in a singleton case presenting a dystrophic myopathy and cerebellar ataxia." (PMID 28544275, 2017). "In addition, genes regulating mitochondrial dynamics, including MSTO1, have been shown to impact other cellular functions including oxidative stress, apoptosis, and mitophagy as well as to induce myopathy and ataxia." (PMID 41303460, 2025). "Two variants (c.571C>T and c.1259delG) in the MSTO1 gene (NM_018116.3) and one variant (c.1068dupT) in the B3GALNT2 gene (NM_152490.2) detected in both of the affected siblings were related to cerebellar atrophy and ataxia." (PMID 36468072, 2022). "MSTO1-related ataxia is an extremely rare disease condition among populations." (PMID 36468072, 2022). "In order to help facilitate an accurate genetic diagnosis, MSTO1 should be included in targeted next-generation-based neuromuscular, mitochondrial and ataxia-related panels, where MSTO1 is currently not included." (PMID 31463572, 2019).
Cerebellar atrophy (6 papers, 2019 to 2026). Cerebellar atrophy is defined as a cerebellum with initially normal structures, in a posterior fossa with normal size, which displays enlarged fissures (interfolial spaces) in comparison to the foliae secondary to loss of tissue. "MRI of patients with recessive mutations in MSTO1 showed cerebellar atrophy and high intensity-signals in the ventricular WM." (PMID 39273172, 2024). "Bi-allelic loss-of-function variants in MSTO1 manifest clinically with a remarkably consistent phenotype of childhood-onset muscular dystrophy, corticospinal tract dysfunction and early-onset non-progressive cerebellar atrophy." (PMID 31463572, 2019). "Although optic atrophy has never been reported, mutations in the Misato Homolog 1 (MSTO1) gene, encoding for a pro-fusion protein, are causative for syndromic diseases characterized by muscular dystrophy, cerebellar atrophy, and pigmentary retinopathy." (PMID 33806088, 2021).
cataract (2 papers, 2019 to 2022). Partial or complete opacity of the crystalline lens of one or both eyes that decreases visual acuity and eventually results in blindness. "Bilateral cataracts and facial dysmorphism observed in the present LETM1 cohort have also been reported in individuals with defective OPA3 and MSTO1, respectively." (PMID 36055214, 2022). "The absence of cataracts and severe intellectual disability appear to distinguish MSTO1-related disorders from MSS." (PMID 31463572, 2019).
congenital myopathy (1 paper, 2017). "Following this finding, we searched for additional patients with pathogenic variants in MSTO1 in the WES datasets from congenital myopathy and congenital muscular dystrophy patients analysed within the NeurOmics project." (PMID 28544275, 2017). "Our results demonstrate that MSTO1 is a novel disease gene causing a mitochondrial morphology defect and leading to a muscular recessive disease (ranging from congenital myopathy to muscular dystrophy) with multisystem involvement." (PMID 28544275, 2017).
mitochondrial myopathy and ataxia (1 paper, 2022). "MSTO1-related mitochondrial myopathy and ataxia (MIM#617675) is caused by monoallelic pathogenic variants in MSTO1 (MIM*617619) leading to an autosomal dominant disease or biallelic variants in MSTO1 leading to a recessive disease." (PMID 36135912, 2022).
mtDNA depletion syndromes (1 paper, 2019). "As impaired mitochondrial fusion is a recognized cause of mtDNA depletion syndromes, this novel link to mtDNA depletion in patient fibroblasts suggests that MSTO1-deficiency should also be considered a mtDNA depletion syndrome." (PMID 31463572, 2019). "Importantly, the degree of mtDNA depletion we see in MSTO1 patient fibroblasts (30–70% of the normal content) is consistent with the levels of mtDNA depletion reported in fibroblasts from OPA1 or MFN2 patients as well as in mtDNA depletion syndromes." (PMID 31463572, 2019).
cancer (3 papers, 2020 to 2022). A tumor composed of atypical neoplastic, often pleomorphic cells that invade other tissues. "Interestingly, many mitochondria-associated ELIdn genes were downregulated in fibroblasts with metastatic transition of cancer, including COX10, MSTO1, CPT2, and MDH1B." (PMID 35565326, 2022).
tumor (3 papers, 2022 to 2023). "Analysis of CHD1L correlated proteins in the tumor tissue revealed that POLR3C, PRKAB2, SETDB1, GPATCH4, and MSTO1 were the top five ones." (PMID 37033447, 2023). "Analysis of RACGAP1 correlated proteins in the tumor tissue revealed that POLR3C, PRKAB2, SETDB1, GPATCH4, and MSTO1 were the top five." (PMID 36430577, 2022).
mitochondrial disease (2 papers, 2017 to 2019). "Since a loss‐of‐function mutation in MSTO1 is associated with impaired mitochondrial dynamics and several symptoms characteristic to mitochondrial disease patients, MSTO1 might be a factor in diseases that have a mitochondrial component." (PMID 28554942, 2017).
intestinal diseases (1 paper, 2017). "Our bioinformatic alignment and calculation on pathogenic proteins for intestinal diseases predicted that MSTO1 indeed shows a close relationship with ACTG2." (PMID 29255146, 2017).
neurodevelopmental disorder (1 paper, 2022). A behavioral and cognitive disorder with onset during the developmental period that involves impaired or aberrant development of intellectual, motor, or social functions. "Five of these genes are already classified as diagnostic grade genes in the IEM panel (COQ4, ELAC2, MRPL44, MSTO1 and SKIV2L) and three others are diagnostic grade genes in different neurology and neurodevelopmental disorder gene panels (EIF2B4, ELP1, EXOSC8)." (PMID 36229886, 2022).
MSTO1 also shares sentences with these, for which no sentence is quoted: myopathy (7 papers); cerebellar ataxia (6); muscular dystrophy (3); optic atrophy (3); Pigmentary retinopathy (2); autism (1); breast carcinoma (1); developmental delay (1); hypothyroidism (1); Intellectual disability (1); liver fibrosis (1); lung carcinoma (1); myasthenia (1); schizophrenia (1).